IGF1 (insulin like growth factor 1)
Diseases named in the same sentence as IGF1 in open-access papers (continued):
Sharing a sentence is not in itself a finding about the gene and the disease.
Hypoglycemia (continued). "We hypothesised that increased IGF-1 concentration could contribute to the susceptibility to develop post-load hypoglycemia." (PMID 24736741, 2014). "The risk of post-load hypoglycemia one year after bariatric surgery increased by 28% with every 10 ng/ml increment of pre-operative IGF-1 serum concentration (OR 1.28; 95%CI: 1.03–1.55; p = 0.0297) and by 18% with post-operative IGF-1 concentrations (OR 1.18; 95%CI: 1.03–1.33; p = 0.0155)." (PMID 24736741, 2014). "IGF-1 serum concentration could be a valuable biomarker to identify patients at risk for hypoglycemia following bariatric surgery independently of a diagnostic OGTT." (PMID 24736741, 2014). "Furthermore, triglycerides and WHR were no longer significant when added to a multiple logistic regression for hypoglycemia risk, indicating the independent relation of IGF-1 to hypoglycemia." (PMID 24736741, 2014). "It is, however, not known whether this is a causal association or whether a low IGF1 concentration is a consequence of exposure to recurrent hypoglycemia." (PMID 23781301, 2012). "In theory, this may explain the association between low levels of total IGF1 and risk of hypoglycemia in pregnant patients with type 1 diabetes." (PMID 23781301, 2012). "Thus, low levels of circulating IGF1 are associated with increased risk of severe hypoglycemia in early pregnancy in women with type 1 diabetes." (PMID 23781301, 2012). "This, in turn, will lead to a change in levels of insulin and other proteins (IGF-1, IGF-binding proteins...) causing hypoglycaemia." (PMID 39931615, 2025). "Individuals with IGF-2-mediated hypoglycemia exhibit fasting hypoglycemia marked by diminished endogenous insulin, ketones, growth hormone, and IGF-1 levels." (PMID 41333493, 2025). "Metabolic problems (22%) included hard-to-control hypoglycemia (n = 2), low IGF-1 (n = 2) (with one individual having normal levels of growth hormone), and elevated total and LDL cholesterol (n = 1)." (PMID 40965981, 2025). "Serum samples drawn prior to hypoglycemia correction revealed an elevated IGF-2:IGF-1 ratio of 60.7 (normal <10) with low paired C-peptide and insulin, consistent with an IGF-2–secreting tumor." (PMID 40270996, 2025). "Patients with IGF-2-mediated hypoglycemia present with fasting hypoglycemia characterised by suppressed endogenous insulin, ketones, growth hormone, and IGF-1." (PMID 38432069, 2024). "In our study, we found a lower IGF‐2:IGF‐1 ratio in patients presenting with hypoglycaemia as the first manifestation of NICTH." (PMID 38411039, 2024). "We therefore compared the induction of hypoglycemia after injection of CV1574-1 or IGF-1 by monitoring blood glucose levels in fasted mice." (PMID 39850478, 2024). "An IGF-2/IGF-1 ratio above 10 is highly suggestive of IGF-2-mediated hypoglycemia if the IGF-2 level is normal or elevated." (PMID 38432069, 2024). "Our analysis of the IGF‐2 to IGF‐1 ratio disclosed lower ratios in patients for whom hypoglycaemia constituted the initial clinical presentation." (PMID 38411039, 2024). "As such, we recommend interpreting the IGF-2/IGF-1 ratio with caution and as part of a holistic evaluation of a patient with unexplained fasting hypoglycemia." (PMID 38432069, 2024). "The therapeutic effect of IGF-1 has been shown in several central nervous system insults, such as hypoglycemia-induced trauma, where IGF-1 increases glucose uptake in neurons through GLUT1 expression." (PMID 38707461, 2024). "It has been reported that, during long-term treatment with IGF-1, approximately half of treated patients develop hypoglycemia." (PMID 39850478, 2024). "Rarely, these tumors can cause paraneoplastic hypoglycemia, known as Doege Potter syndrome characterized by hypoglycemia due to the tumor's production of insulin-like growth factor-1 (IGF-1)." (PMID 39161563, 2024). "One of the most common adverse effects is hypoglycemia, which is related to the impact of IGF-1 on glucose metabolism." (PMID 39529965, 2024).
Hypoglycemia (continued). "Other blood analytes with altered levels were adrenocorticotropic hormone (ACTH) and insulin-like growth factor-1 (IGF-1) in a sample collected during an episode of severe hypoglycemia." (PMID 37308982, 2023). "Further, due to the direct influence of IGF-1 on glucose metabolism, individuals receiving IGF-1 must be closely monitored for hypoglycemia." (PMID 36833418, 2023). "An interesting case reported by Schröder and co-workers in 2009 describes a 54-year-old female patient with hypoglycemia and elevated IGF-1 and growth hormone levels." (PMID 37371827, 2023). "Laboratory exam on admission demonstrated hypoglycemia accompanied with low serum insulin and IGF1 levels." (PMID 36742395, 2023). "This explains why a mechanism of GH resistance with respect to IGF-1 secretion can be triggered to maintain normal glucose levels and prevent hypoglycemia." (PMID 37895086, 2023). "We have interpreted these slightly increased levels of ACTH and IGF-1 as a normal defense mechanism, provided that they are counterregulatory hormones and the patient had severe hypoglycemia when the blood sample was collected." (PMID 37308982, 2023). "The differential diagnosis of hypoglycemia should include rare causes such as DPS, and the IGF-2/IGF-1 ratio is a useful tool." (PMID 37373678, 2023). "Under fasting conditions, elevated GH levels are important to prevent hypoglycaemia and mobilize free fatty acids from adipose tissue, while reduced IGF-1 impairs growth and preserves energy for vital life processes." (PMID 37895086, 2023). "Laboratory examinations revealed that fasting hypoglycemia, GH, and IGF-1 levels were lower than the measurable values, along with a low fasting C-peptide level." (PMID 36034453, 2022). "We recommend examining patients for primary or secondary hypoadrenalism, IGF-1, C-peptide, ketones, sulfonylurea concentrations, and in some instances insulin in cases of unprovoked hypoglycemia in a diabetic." (PMID 34583764, 2021). "Billemont and colleagues proposed several potential mechanisms for TKI-induced hypoglycemia including capillary regression of pancreatic islets, IGF-1 modulation, and a reduction of glucose uptake in the context of concomitant gastrointestinal toxicity." (PMID 33841146, 2021). "Fetal hypoglycemia occurs, stimulating protein catabolism, and there is a reduction in the insulin-like growth factor (IGF-1)." (PMID 33440405, 2021). "Recombinant human (rh) IGF-1 has already been investigated as a treatment to improve outcome after intestinal epithelial damage, but electrolyte imbalances and hypoglycemia have complicated its use." (PMID 32793242, 2020). "In the differential diagnosis in those presenting with hypoglycemia, it was necessary to exclude insulinomas, adrenal insufficiency, hypothyroidism and IGF1, IGF2 producing tumors." (PMID 32813762, 2020). "The animals also exhibited other complications such as curved spines, decreased subcutaneous fat, hypoglycemia, and lowered levels of IGF-1." (PMID 33442387, 2020). "Her growth was suboptimal with a GH concentration of 0.6 ug/L in response to hypoglycaemia with an undetectable serum IGF-1 and a low IGFBP3 (0.75 mg/L; NR 0.8–3.9)." (PMID 32060556, 2020). "•GHR-deficient pigs show markedly reduced serum IGF1 and IGFBP3 levels, and transient juvenile hypoglycemia." (PMID 29678421, 2018). "High doses of IGF-1 administration typically results in hypoglycaemia despite the potent suppression of circulating insulin concentrations it triggers." (PMID 26733412, 2016). "Many of the same AEs were likely to occur among patients during the placebo phase, including hypoglycemia (3 occurrences; N = 2), albeit less frequently; significantly more AEs were reported when patients were taking IGF-1 than placebo (P = 0.0015)." (PMID 25685306, 2014).
Hypoglycemia (continued). "The most common side effects during the IGF-1 treatment phase were sleep disturbance (N = 7); hypoglycemia ((<50 mg/dL) (7 occurrences; N = 5)), constipation (N = 4), increased appetite (N = 4), and mood changes or increased irritability (N = 4)." (PMID 25685306, 2014). "Due to its insulin-like action, the most common side-effect to exogenous IGF-1 is hypoglycemia, which occurs in a dose-dependent manner." (PMID 24736741, 2014). "Our data identified IGF-1 as a novel predicting factor for the occurrence of post-prandial hypoglycemia following bariatric surgery." (PMID 24736741, 2014). "When we analysed other differences in other pre-operative parameters with respect to post-load hypoglycemia, we found that only IGF-1 and age were significantly different between patients with hypoglycemia and euglycemia." (PMID 24736741, 2014). "In summary, the results from our study have clearly demonstrated that the serum GH concentrations in patients with HH do rise during the episode of hypoglycaemia whilst the IGF-1 levels are relatively low." (PMID 24228030, 2013). "The serum GH concentration at the time of hypoglycemia was noted to rise to a mean level of 12.5 μg/liter whilst the mean IGF-1 and IGFBP3 concentrations were low at 29.2 ng/mL and 1.21 mg/L, respectively." (PMID 24228030, 2013). "In the absence of IGF2 assays, low serum insulin in combination with low IGF1 levels at the time of hypoglycemia is helpful in making the diagnosis of NICTH." (PMID 24616774, 2013). "IGF-1 complexed with binding protein 3 (Somatokine R) used in this study was developed to prolong the half-life and reducing side effects (including hypoglycemia)." (PMID 22778966, 2012). "Growth hormone stimulatory tests were made and insulin provocative test revealed a severe GH deficiency in this patient, defined by a peak response to insulin-induced hypoglycemia less than 3 ng/dl and IGF1 concentrations less than -2SDS." (PMID 19128470, 2009). "Insulin provocative test revealed a severe GH deficiency in these patients, defined by a peak response to insulin-induced hypoglycemia less than 3 ng/dl and IGF1 concentrations less than – 2SDS." (PMID 19128470, 2009). "The other adverse effect of the use of rhIGF-1 observed in GH receptor-deficient patients is hypoglycemia, due to low levels of IGFBP3 and increased level of free IGF-1 available for binding to insulin receptors." (PMID 17676425, 2008). "The APX ratswhen compared to normals had a greater sensitivityto insulin-induced hypoglycemia while IGF-1 decreasedthe plasma glucose to a lesser degree in APXrats." (PMID 11469391, 2000). "However, IGF-1 treatment has significant potential adverse effects including hypoglycemia, lymphoid overgrowth, benign intracranial pressure, coarsening of facial features, and, similar to GH, a theoretical increased risk of malignancies." (PMID 39850478, 2024). "One adverse effect of IGF-1 treatment is hypoglycemia due to its insulin-like action." (PMID 39850478, 2024). "Notably, subcutaneous CV1574-1 did not lower the blood glucose levels compared to saline, indicating that subcutaneous CV1574-1 has less tendency to induce hypoglycemia than does IGF-1." (PMID 39850478, 2024). "Thus, the effect of IGF-1 on glucose metabolism is similar to insulin (insulin-like effect) and—in contrast to GH—promotes hypoglycaemia." (PMID 37895086, 2023). "Since both hGH and IGF-1 have a direct influence on glucose metabolism, mimicking the anabolic effect of insulin, and because hypoglycemia is a potential side effect in individuals treated with IGF-1, we correlated the metabolic response to these two compounds to the baseline glucose metabolism." (PMID 36833418, 2023). "Additionally, preterm pigs have low circulating IGF-1 levels and immature immune, gut, and metabolic systems, making them sensitive to sepsis, hypoglycemia, and gut disorders such as NEC, for which they are a clinically relevant model of preterm infants." (PMID 36973010, 2023).
Hypoglycemia (continued). "Our last specific question related to the risks (e.g. tumours, hypoglycemia, cardiac hypertrophy, other soft tissue overgrowth) and benefits (assessed by A1c) of recombinant human IGF-1 (rhIGF-1) or IGF-1/IGFBP3 composite in patients with pathogenic INSR variants." (PMID 37794082, 2023). "In sheep, FGR induced by placental embolization results in fetal hypoxia and hypoglycemia and is associated with reductions in SLC2A1 mRNA and placental glucose uptake, but the intra-amniotic infusion of IGF1 into these fetuses increased the placental expression of SLC2A1 mRNA." (PMID 37374044, 2023). "Administration of IGF-1 may induce severe hypoglycemia due to its molecular structure and functional similarity with insulin." (PMID 35847048, 2022). "Preterm pigs delivered at 90% gestation show morbidities similar to those in many preterm infants, including reduced growth, impaired postnatal gut, brain and immune development, neonatal hypoglycemia and reduced IGF-1 levels, relative to their term-born counterparts." (PMID 35989990, 2022). "At the time of hypoglycemia, suppressed serum insulin, GH and IGF-1 levels was found." (PMID 36211262, 2022). "With regards to safety, hypoglycemia is the most commonly seen short-term effect of IGF-1 use, although accumulation of body fat, coarsening of facial features, and lymphoid hyperplasia necessitating surgical correction have also been observed with long-term use." (PMID 34249891, 2021). "Recent work suggests that cooperative action of insulin and insulin-like growth factor 1 (IGF-1) promotes astrocyte glucose uptake and may be important for the neural response to hypoglycaemia." (PMID 31765625, 2020). "Various abnormalities related to glucose homeostasis, such as hypoinslulinemia, hypoglycemia, increased insulin sensitivity, decreased serum growth hormone level and reduced hepatic IGF-1 expression, could be observed in mutant animals before death." (PMID 27293546, 2016). "Thus, IGF-1 is known to enhance insulin sensitivity in humans and recombinant IGF-1 induces hypoglycemia as does its ectopic secretion." (PMID 24736741, 2014). "Notably, post-operative IGF-1 concentration was significantly higher in patients with post-load hypoglycemia (n = 18) compared to patients with euglycemia (n = 17)." (PMID 24736741, 2014). "However, plasma concentrations of IGF-1 and IGF-2 can be 1000 times greater than insulin in NICTH allowing them to cause hypoglycemia." (PMID 24934576, 2014). "Finally, IGF-1 serum concentrations before and after surgery significantly predicted post-load hypoglycemia with odds ratios of 1.28 (95%CI:1.03–1.55, p = 0.029) and 1.18 (95%CI:1.03–1.33, p = 0.015), respectively, for each 10 ng/ml increment." (PMID 24736741, 2014). "Interestingly, patients with post-load hypoglycemia had significantly higher serum IGF-1 concentrations compared to patients with euglycemia, already before surgery (145±12 ng/dl vs. 105±9 ng/dl respectively, p = 0.0122)." (PMID 24736741, 2014). "Moreover pre-operative IGF-1 serum concentration was the only parameter to be detected before surgery that predicted post-load hypoglycemia." (PMID 24736741, 2014). "Given the direct effect of IGF-1 on glucose metabolism we hypothesised that IGF-1 is an indicator for the occurrence of post-prandial hypoglycemia in patients who underwent bariatric surgery." (PMID 24736741, 2014). "Interestingly, both pre- and post-operative IGF-1 serum concentrations were significantly higher in subjects with post-load hypoglycemia and the pre-operative levels correlated negatively with 2 h glucose concentration." (PMID 24736741, 2014). "Furthermore, systemic delivery of IGF-1 can be associated with undesirable side effects such as weight gain, hypoglycemia and tumorigenesis due to IGF-1’s effects on multiple organ systems." (PMID 23826235, 2013). "IGF1 levels were associated with the occurrence of severe hypoglycemia neither in the entire cohort (r=0.002, P=0.30) nor in any gender." (PMID 23781301, 2012).
Hypoglycemia (continued). "Levels of IGF1 were associated with the frequencies of neither mild symptomatic hypoglycemia (P=0.24) nor biochemical hypoglycemia (P=0.089) nor with the class of hypoglycemia awareness (P=0.14)." (PMID 23781301, 2012). "Levels of IGF1 were associated with neither mild symptomatic hypoglycemia (P=0.24) nor biochemical hypoglycemia (0.089) nor hypoglycemia awareness (P=0.16)." (PMID 23781301, 2012). "Moreover, Sirt6 knockout (ko) mice are born normally but quickly exhibit characteristics of premature aging with profound lymphopenia, severe hypoglycemia, and greatly reduced serum levels of insulin-like growth factor 1 (IGF-1), ultimately leading to early death by around 4 weeks." (PMID 38016059, 2023). "Therefore, a GHR-KO pig model characterized by low IGF1 levels and juvenile hypoglycemia was used." (PMID 37189345, 2023). "Consequently, high IGF-1 serum levels would be associated with hypoglycemia before and after bariatric surgery independent of insulin secretion." (PMID 24736741, 2014). "Hypoglycemia is further exacerbated by IGF-2 binding to IGF-1R and IR at the pancreatic alpha cells and hypothalamus, which mimics the effects of insulin and IGF-1 to suppress secretion of counterregulatory hormones—glucagon and GH." (PMID 41179270, 2025). "This often presents as symptomatic fasting hypoglycemia, endogenous insulin and ketones suppression, and an elevated IGF-2/IGF-1 ratio." (PMID 40727482, 2025). "Serum samples were drawn for IGF-2, IGF-1, IGF binding protein 3 (IGFBP-3), insulin, proinsulin, and C-peptide prior to hypoglycemia correction." (PMID 40270996, 2025). "When there is localised disease, surgical resection is curative with resolution of hypoglycemia and normalisation of the IGF-2/IGF-1 ratio in most cases." (PMID 38432069, 2024). "Subsequent laboratory investigations demonstrated lowered IGF-1 and elevated IGF-2 levels, indicative of an IGF-2-producing tumor as the etiology of the hypoglycemia." (PMID 38666048, 2024). "Beyond the interplay of glucose and IGF1, CSH is significantly elevated in fetal circulation as a result of fetal hypoglycemia." (PMID 37374044, 2023). "Subsequent measurement of the serum IGF2:IGF1 ratio was elevated at 22.3 and consistent with IGF-2 mediated hypoglycemia and imaging studies demonstrated a pelvic mass." (PMID 36303203, 2022). "Results showed a serum IGF-2 of 78.2 nmol/L, IGF-1 of 3.5 nmol/L (4.4–21.8) and an IGF-2:IGF-1 ratio of 22.3 which is consistent with IGF-2 mediated hypoglycemia." (PMID 36303203, 2022). "IGF-1 stimulates TSH and the proliferation of thyroid tissue that leads to increased secretion of thyroid hormones and consequent hypoglycemia." (PMID 31080828, 2019). "In NICTH, there are mainly three mechanisms leading to hypoglycemia: tumor cells secrete excessive high-molecular-weight IGF-2 precursor, IGF-1, and insulin." (PMID 29166433, 2019). "In this context, repeated evaluations of plasma cortisol, ACTH and GH concentrations during spontaneous hypoglycemia, as well as FT4 and IGF-1 concentrations should be measured." (PMID 26829045, 2016). "Multiple logistic regression for post-operative parameters including IGF-1, age, triglycerides and WHR revealed that only IGF-1 significantly predicted the occurrence of post-load hypoglycemia (OR 1.22; 95%CI: 1.02–1.42, p = 0.0300)." (PMID 24736741, 2014). "This may also explain the lack of association between IGF1 levels and severe hypoglycemia." (PMID 23781301, 2012). "The main problems in IGF-1 treatment include BBB permeability, side-effects like hypoglycemia, and short intervals in administration of the drug." (PMID 22778966, 2012). "Glucose values remained within normal range, consistent with no signs of hypoglycemia in a recent clinical IGF-1 trial." (PMID 38086951, 2024). "Fifth, no biochemical data (e.g., plasma glucose and prevalence of hypoglycaemia, growth hormone, insulin-like growth factor 1, Ca2+, Mg2+, etc.)of included newborns were collected." (PMID 36443400, 2023).